ENSG00000252722
Synonyms: LOC124900369
Gene: Small Cajal body-specific RNA gene on chromosome 15 (75,121,536 to 75,121,666, reverse strand). Ensembl gene ENSG00000252722.
Gene Ontology:
Biological process: RNA processing
Cellular component: Cajal body; nucleolus